DAPP1 (dual adaptor of phosphotyrosine and 3-phosphoinositides 1)
Description:
May act as a B-cell-associated adapter that regulates B-cell antigen receptor (BCR)-signaling downstream of PI3K.
Synonyms: BAM32
Tractability: Antibody: UniProt places it where antibodies can reach, with high confidence; its Gene Ontology location is reachable by antibodies, with high confidence. PROTAC: ubiquitination databases record sites on it; its protein half-life has been measured.
Gene: Protein-coding gene on chromosome 4 (99,816,816 to 99,870,190, forward strand). Ensembl gene ENSG00000070190.
Subcellular location: Cytoplasm; Membrane
Pathways (Reactome):
Immune System: Antigen activates B Cell Receptor (BCR) leading to generation of second messengers
Gene Ontology:
Molecular function: phosphatidylinositol-3,4,5-trisphosphate binding; phosphatidylinositol-3,4-bisphosphate binding; protein binding; phospholipid binding
Biological process: protein dephosphorylation; signal transduction
Cellular component: plasma membrane; cytosol; cytoplasm; membrane
Genetic constraint (gnomAD): Loss-of-function variants: 13 observed, 22.84 expected, observed/expected ratio (o/e) 0.57, 90% interval 0.37 to 0.9. The upper end of that interval is the gene's LOEUF score, 0.9, which puts it in group 3 of 6, group 1 being the genes least tolerant of losing a copy. Missense variants: 180 observed, 241.49 expected, observed/expected ratio (o/e) 0.75, 90% interval 0.66 to 0.84. Synonymous variants: 85 observed, 84.92 expected, observed/expected ratio (o/e) 1, 90% interval 0.84 to 1.2.
Homologues: Orthologues: chimpanzee DAPP1 (100% identical), macaque DAPP1 (98% identical), rabbit DAPP1 (94% identical), pig DAPP1 (94% identical), mouse Dapp1 (93% identical), rat Dapp1 (92% identical), dog DAPP1 (89% identical), guinea pig DAPP1 (88% identical), tropical clawed frog dapp1 (68% identical), zebrafish dapp1 (63% identical). Paralogues in human: GRAP2 (20% identical), SLA2 (18% identical), GRAP (16% identical), GRB2 (16% identical), NCK1 (16% identical), NCK2 (16% identical), SLA (15% identical), SH2D5 (13% identical), GRAPL (8% identical).
Diseases named in the same sentence as DAPP1 in open-access papers:
DAPP1 is named in the same sentence as 24 diseases in open-access papers, as found by Europe PMC text mining. Sharing a sentence is not in itself a finding about the gene and the disease. The quoted sentences say what the papers report.
breast carcinoma (2 papers, 2017 to 2021). "The genes sharing these GO terms have been previously shown to be involved in breast cancer prognostic process (e.g., CXCR6, KIT, RUNX3) and also immune cell regulation (e.g., CD8B, DAPP1, LY75)." (PMID 33919884, 2021).
acute myeloid leukemia (1 paper, 2025). Acute myeloid leukemia (AML) is a group of neoplasms arising from precursor cells committed to the myeloid cell-line differentiation. "Across diverse datasets—including human hematopoiesis, acute myeloid leukemia, mouse endocrinogenesis, Dapp1 knockout and irradiation injury—scRL outperformed benchmark fate-inference and pseudotime methods, revealed novel regulators and mapped dynamic fate biases (see Results)." (PMID 40563931, 2025).
Alzheimer disease (1 paper, 2013). A progressive, neurodegenerative disease characterized by loss of function and death of nerve cells in several areas of the brain leading to loss of cognitive function such as memory and language. "This network contains the proinflammatory cytokine Il1a, previously associated with Alzheimer’s disease, development and plasticity, immune associated genes (Cd80, Cr2, Cd27, Dapp1) and chemokines (Ccl3, Ccl4, Ccl21)." (PMID 23742273, 2013).
asthma (1 paper, 2019). "However, a large human GWAS did not reveal any main effect associations between the DAPP1 locus and asthma, including with SNPs that yielded strong multi-tissue cis eQTLs for DAPP1 and other genes in the syntenic region." (PMID 31869344, 2019). "Moreover, DAPP1 expression in the lung was highly positively correlated with a panel of pro-inflammatory cytokines, including several that have been implicated in asthma, such as IL1A, IL7, IL12A, IL17A, IL23A, and IL33." (PMID 31869344, 2019). "Of these, we prioritized Dapp1 because of its known role in mediating activation of and interactions between immune cells, its expression profile in tissues relevant to asthma, and the high correlation of its mRNA levels with those of several asthma-related inflammatory cytokines in humans." (PMID 31869344, 2019). "At one locus in particular, we functionally demonstrated that Dapp1 modulates lung resistance in response to DEP exposure, thus providing evidence for a novel GxE interaction that influences asthma-related traits in mice." (PMID 31869344, 2019). "Additional studies will be needed in order to obtain a more definitive understanding of how Dapp1 function influences AHR and its relevance to the biological mechanisms and GxE interactions of asthma in humans." (PMID 31869344, 2019).
atherosclerosis (1 paper, 2024). A disease characterized by the build-up of fatty material and calcium deposition in the arterial wall resulting in partial or complete occlusion of the arterial lumen. "Then, KEGG pathway analysis revealed that these genes were enriched in “lipid and atherosclerosis” (Ncf1, Eif2s1, Tank, Vav1, Nfe2l2), “B-cell receptor signaling pathway” (Blnk, Dapp1, Vav1), and “Fc gamma R-mediated phagocytosis” (Prkcg, Ncf1, Vav1)." (PMID 38952478, 2024).
cervical cancer (1 paper, 2021). A primary or metastatic malignant neoplasm involving the cervix. "Therefore, plasma exosomal RGS18 may be more associated with cervical cancer development and progression than the other three mRNAs (KIF2A, ARL6IP5, and DAPP1)." (PMID 34827689, 2021).
chronic graft versus host disease (1 paper, 2025). Chronic graft versus host disease (GVHD) is a complication that can occur after a stem cell or bone marrow transplant in which the newly transplanted donor cells attack the transplant recipient's body. "In another study that investigated lncRNA expression in chronic graft-versus-host disease, three lncRNAs (NONHSAT142151, NONHSAT040475 and FR118417) were found to strongly correlate with the expression of mRNAs related to the BCR signaling pathway (BTK, CD72, DAPP1, LILRB3, NFKBIE, RASGRP3)." (PMID 39940921, 2025).
Crohn disease (1 paper, 2023). A gastrointestinal disorder characterized by chronic inflammation involving all layers of the intestinal wall, noncaseating granulomas affecting the intestinal wall and regional lymph nodes, and transmural fibrosis. "ROC analysis demonstrated excellent predictive ability of DAPP1 and ELL2 for intestinal inflammation in Crohn’s disease, with AUCs exceeding 0.8." (PMID 38059894, 2023). "Similarly, DAPP1 and ELL2 were upregulated in Inflamed Crohn’s disease samples." (PMID 38059894, 2023).
dementia (1 paper, 2024). Loss of intellectual abilities interfering with an individual's social and occupational functions. "Four protective proteins (PLEK, DAPP1, CSK and CASP3) that decreased postinfection in the BLSA were significantly decreased in dementia cases in the ARIC study, with several other protective proteins (EIF4A1, DSG1, PIK3CG, PRKCB and LYN) showing similar trends." (PMID 39143319, 2024).
tumor (4 papers, 2015 to 2025). "Of 22 differentially methylated promoters common between all LS tumor groups, seven inversely correlated with expression: ADHFE1, DAPP1, FBLIM1, GRIA4, HOXA3, KLF17, and ZNF528." (PMID 40753397, 2025). "However, studies have shown that the lack of DAPP1 can promote anti-tumor response and increase the expression of Tim3 in CD8+ T cells." (PMID 40842594, 2025).
cancer (1 paper, 2021). A tumor composed of atypical neoplastic, often pleomorphic cells that invade other tissues. "According to a preclinical study, DAPP1 deficiency could not efficiently activate antigen-specific T cells, suggesting that DAPP1 downregulation is associated with a weakness in cancer-specific immunity." (PMID 34827689, 2021). "The combination of miRNA (miR-142-3p), mRNAs (CXCL5, KIF2A, RGS18, APL6IP5, and DAPP1), and snoRNAs (SNORD17, SCARNA12, SNORA6, SNORA12, SCRNA1, SNORD97, SNORD62, and SNORD38A) clearly distinguished the normal samples from the cancer group samples." (PMID 34827689, 2021).
DAPP1 also shares sentences with these, for which no sentence is quoted: parasitemia (3 papers); autism (2); infection (2); adenoma (1); African Trypanosomiasis (1); COVID-19 (1); developmental delay (1); Hepatomegaly (1); influenza (1); Intellectual disability (1); Nephropathy (1); peritonitis (1); Splenomegaly (1).